KDM2B (lysine demethylase 2B)
Diseases named in the same sentence as KDM2B in open-access papers (continued):
Sharing a sentence is not in itself a finding about the gene and the disease.
autism (4 papers, 2020 to 2023). Persistent deficits in social interaction and communication and interaction as well as a markedly restricted repertoire of activity and interest as well as repetitive patterns of behavior. "In line with this, KDM2B is among the most frequently deleted genes in the 12q24.31 microdeletion syndrome, which is characterized by principal clinical features including autism, intellectual disability, epilepsy, and craniofacial anomalies." (PMID 31317506, 2020). "We observed an increased expression of the lncRNA A930024E05Rik, also known as LncKdm2b, which positively regulates the transcription of Kdm2b, a histone demethylase that is important for neural development and plays a role in autism and syndromic intellectual disability." (PMID 32545722, 2020).
diffuse large B-cell lymphoma (4 papers, 2018 to 2024). "Herein we show that FBXL10 (also called KDM2B or JHDM1B), an important member of Polycomb repressive complexes, is overexpressed in human diffuse large B-cell lymphoma (DLBCL) tissues and the derived cell lines." (PMID 29352142, 2018).
lung carcinoma (4 papers, 2019 to 2023). "For example, KDM2B knockdown in human lung cancer cells led to increased cell viability and decreased cytotoxicity in response to treatment with the chemotherapeutic drug cisplatin." (PMID 37773725, 2023).
prostate carcinoma (4 papers, 2019 to 2024). A carcinoma that arises from epithelial cells of the prostate gland. "The expression of KDM2B in prostate cancer CTCs was examined by immunofluorescence using antibodies for CK, KDM2B, and CD45." (PMID 38903530, 2024). "In the same study, we explored the expression of KDM2B in CTCs of a small cohort of prostate cancer patients." (PMID 38903530, 2024). "Based on the previous data the current study investigated at protein level the expression of ORAI1, STIM1, and KDM2B in CTCs from prostate cancer patients." (PMID 38903530, 2024). "We have also recently shown that overexpression of KDM2B in prostate cancer cells resulted in a significant upregulation of ORAI1 and Stim1 transcription." (PMID 38903530, 2024). "The Coremine website finds approximately 18, 250, and 4 articles for FOXP1, RELA, and KDM2B related to prostate cancer." (PMID 37403016, 2023). "This study confirmed the increased expression of KDM2B in CTCs from prostate cancer patients revealing that 85% of the patients harbored KDM2B-positive CTCs, which is line with the results from the smaller group of patients, implying that this expression is a common phenomenon for prostate cancer." (PMID 38903530, 2024).
colorectal cancer (3 papers, 2019 to 2023). A primary or metastatic malignant neoplasm that affects the colon or rectum. "Moreover, EZH2, along with the potential epigenetic regulator lysine-specific demethylase 2B (KDM2B), dampens colorectal cancer migration, invasion, and maintenance of cancer stem cells via the PI3K/AKT pathway." (PMID 36672374, 2023). "Relationship between KDM2B expression and clinicopathologic parameters in colorectal cancer." (PMID 33791221, 2021).
diabetes (3 papers, 2019 to 2025). "When comparing the two forms of diabetes, the methylation dysregulation for the CpG site in KDM2B is in the opposite direction in T2D signifiying the differences between the two diseases, and may be a contributing factor to the increased OXPHOS." (PMID 36662841, 2023).
latent infection (3 papers, 2020 to 2025). "CMV latent infection associated hyper-methylated CpG sites are enriched in PcG proteins including RNF2, EZH2, KDM2B and JARID2." (PMID 39360678, 2024). "As miR-M6-5p increases the transcriptionally repressive marks the H3K27me3 on viral genome and maintains latent infection by targeting KDM2B, histone H3K27me3 modification could possibly be involved in regulating latent infection of MDV." (PMID 39840986, 2025). "We assumed that miR-M6-5p might modulate the latent MDV epigenome by targeting KDM2B, thus regulating viral gene expression and latent infection." (PMID 39840986, 2025).
osteosarcoma (3 papers, 2019 to 2024). A usually aggressive malignant bone-forming mesenchymal neoplasm, predominantly affecting adolescents and young adults. "Since KDM2B acetylation at K758 has the ability to mediate the transcription of p21 and puma, two key genes in modulating tumour cells growth and apoptosis, we next investigated whether KDM2B acetylation was implicated in the carcinogenesis of osteosarcoma." (PMID 31218831, 2019). "In conclusion, this study demonstrates that KDM2B is acetylated in human osteosarcoma cells, and the acetylation is mediated by Tip60 and occurs in K758." (PMID 31218831, 2019). "Moreover, it has been reported that KAT5 regulates the acetylation of KDM2B to enhance progression of osteosarcoma." (PMID 35333774, 2022). "In the current study, we found that KDM2B was acetylated in osteosarcoma cancer cells." (PMID 31218831, 2019). "Moreover, Tip60‐dependent acetylation of KDM2B enhanced its pro‐proliferating and pro‐metastatic effects on osteosarcoma cells and in vivo tumour growth." (PMID 31218831, 2019). "The high occurrence of KDM2B acetylation at K758 in osteosarcoma cells indicated that the oncogenic activities of KDM2B might depend on its acetylation at K758." (PMID 31218831, 2019). "In the present study, we investigated if KDM2B acetylation could be involved in the onset and progression of osteosarcoma." (PMID 31218831, 2019). "KDM2B is acetylated at lysine 758 by Tip60 in human osteosarcoma cells." (PMID 31218831, 2019). "In this study, acetylation of KDM2B was observed in human osteosarcoma cell lines (MG‐63 and HOS)." (PMID 31218831, 2019). "Moreover, whether Tip60 is responsible for the acetylation of KDM2B in osteosarcoma cells was studied." (PMID 31218831, 2019).
synovial sarcoma (3 papers, 2019 to 2025). "A similar phenomenon was clear from ChIP-Seq for KDM2B in mouse synovial sarcomas after treatment with vehicle or decitabine or 5-AZA, with a diminution of ChIP-Seq enrichment at the promoters of known fusion target genes." (PMID 40299558, 2025). "Overall, these results reject the hypothesized mechanism for reduced expression of canonical synovial sarcoma target genes by reduced recruitment of fusion and KDM2B to these loci." (PMID 40299558, 2025). "The SSXRD domain has been studied in the context of synovial sarcomas where it was found to associate with the CpG binding protein CXXC2 (KDM2B) which is a component of a non-canonical polycomb complex." (PMID 31237565, 2019). "Using ChIP-Seq, we observed regions where decitabine treatment led to the acquisition of new or increased binding sites for SS18::SSX and KDM2B in HS-SY-II human synovial sarcoma cells that did not correspond to previous KDM2B sites." (PMID 40299558, 2025).
Viral infections (3 papers, 2020 to 2024). "Viral infections alter the expression of lysine demethylase 2B (KDM2B/NDY1), enhancer of zeste 2 polycomb repressive complex 2 subunit (EZH2) and JARID2." (PMID 39420919, 2024). "Remarkably, cells with overexpressed KDM2B showed enhanced cell proliferation for 8 days following viral infection relative to cells transduced with the empty vector, suggesting that KDM2B promotes cell proliferation." (PMID 33029857, 2020). "Thus, the characterization of the role of NuRD, Tip60, and KDM2B factors in viral infections can help better understanding of different viral pathogeneses." (PMID 31923286, 2020). "Importantly, NuRD, Tip60, and KDM2B have also been shown to be able to control other viral infections and viral pathogenesis such as in the case of human papillomavirus, human cytomegalovirus, Epstein-Barr virus, arbovirus, and influenza virus infections." (PMID 31923286, 2020).
Acute Lymphoblastic Leukaemia (2 papers, 2018 to 2022). "Acute Lymphoblastic Leukaemia (AML): As seen in normal mouse and human haemopoietic stem and progenitor cells (HSPC), KDM2B is highly expressed in lymphoblastic leukaemic stem cells, and is required for their maintenance." (PMID 35406676, 2022).
Burkitt lymphoma (2 papers, 2018). A rare form of malignant mature B-cell non-Hodgkin lymphoma. "Interestingly, KDM2B was also recently found to be silenced by EBV in Burkitt lymphoma cell lines, through DNA methylation." (PMID 30135119, 2018). "However, so far, no study has assessed the potential role of KDM2B in the development of EBV-positive Burkitt lymphoma." (PMID 30135119, 2018).
cervical cancer (2 papers, 2018 to 2021). A primary or metastatic malignant neoplasm involving the cervix. "This study suggested that the ALX3 increased CDC25A expression through KDM2B-mediated demethylation of H3K4me3, which induced proliferation and cell cycle progression of cervical cancer cells." (PMID 34266408, 2021). "In cervical cancer and keratinocyte cell lines, overexpression of miR-146a-5p inhibited proliferation and migration by targeting lysine-specific demethylase 2B (KDM2B)." (PMID 30563114, 2018). "Interestingly, knockdown of KDM2B has once been reported to suppress proliferation of cervical cancer cells." (PMID 34266408, 2021).
colon cancer (2 papers, 2021). "Expression of KDM2B protein in the normal colon tissue and colon cancer tissue." (PMID 33791221, 2021). "However, in colon cancer cells, it remains unclear whether KDM2B-induced EMT was dependent on its histone demethylase activity or PRC1 activity." (PMID 33779563, 2021). "A previous report showed that KDM2B knockdown and overexpression influenced the expression of both epithelial and mesenchymal genes in HCT116 colon cancer cell line, indicating a relationship between KDM2B expression and EMT." (PMID 33779563, 2021).
COVID-19 (2 papers, 2022). A disease caused by infection with severe acute respiratory syndrome coronavirus 2. "Although there are no COVID-19-related reports, KDM2B is a histone dimethyltransferase that has been reported to bind to the viral epigenome and its expression was affected by viral proteins or conversely regulated viral gene expression." (PMID 36451245, 2022).
developmental delay (2 papers, 2023 to 2025). "The KDM2B-CxxC disorder is characterized by developmental delays, mainly in the speech and motor domain, variable intellectual disability, congenital heart defects and facial dysmorphism." (PMID 40420380, 2025).
myeloid leukemia (2 papers, 2021 to 2023). A clonal proliferation of myeloid cells and their precursors in the bone marrow, peripheral blood, and spleen. "Two complementary studies suggested an oncogenic role for KDM2B in myeloid leukemia." (PMID 34944554, 2021).
Retinal coloboma (2 papers, 2018 to 2021). A notch or cleft of the retina or choroid, located vertically below the optic disc. "Fbxl10 (Kdm2b) is a JmjC domain-containing histone demethylase; homozygous mutation in FbxI10 results in neural tube closure defects, an expanded retina and retinal coloboma." (PMID 33563331, 2021). "On the other hand, the mice lacking the full length KDM2B-LF protein, but retaining the short KDM2B-SF isoform, exhibit a not fully penetrant phenotype with 40% of the mutants exhibiting retinal coloboma and only 44% of knockouts displaying fatal neural tube closure defects." (PMID 30059280, 2018).
Sepsis (2 papers, 2023 to 2024). Sepsis is defined as life-threatening organ dysfunction caused by a dysregulated host response to infection. "To further understand the mechanism underlying circMAPK1/WNK1 axis in sepsis-induced lung injury, we first examined the expression of KDM2B and WNK1 in septic patients." (PMID 39300342, 2024). "The model and KDM2B knockdown provided effective platforms for studying KDM2B's role in regulating sepsis‐associated AKI." (PMID 37773725, 2023). "The results above suggested that KDM2B knockdown repressed LPS‐induced inflammation in sepsis‐associated AKI." (PMID 37773725, 2023). "In sum, KDM2B knockdown reduces LPS‐induced oxidative stress in sepsis‐associated AKI." (PMID 37773725, 2023). "KDM2B knockdown reduced cytotoxicity, inflammation and oxidative stress in LPS‐induced AKI via inhibiting NF‐κB and AP‐1 pathways, indicating KDM2B may be a promising therapeutic target for the treatment of sepsis‐associated AKI." (PMID 37773725, 2023). "Targeting KDM2B may be a promising strategy for the treatment of sepsis‐associated AKI." (PMID 37773725, 2023). "There was a negative correlation between circMAPK1 and WNK1, as well as between circMAPK1 and KDM2B, while WNK1 positively correlated with KDM2B in patients with sepsis-induced lung injury." (PMID 39300342, 2024). "Our study demonstrated that UPF1 serves as a RBP of circMAPK1 to promote KDM2B mRNA decay in sepsis-induced lung injury." (PMID 39300342, 2024). "This study lies in its contribution to the nuanced understanding of the molecular interactions in sepsis, and circMAPK1/KDM2B/WNK1/NLRP3 axis was identified as a promising target for the targeted therapeutic strategy of sepsis-induced ALI." (PMID 39300342, 2024). "Our findings illustrated a decrease in KDM2B expression in patients with sepsis, and circMAPK1-recruited UPF1 modulating its mRNA stability." (PMID 39300342, 2024). "CircMAPK1 exacerbates sepsis-induced lung injury by destabilizing KDM2B mRNA to suppress WNK1 expression, thus facilitating NLRP3-driven macrophage pyroptosis." (PMID 39300342, 2024). "However, the specific role of KDM2B in potentially mediating the hypermethylation of WNK1 in sepsis-induced ALI remains an area for further investigation." (PMID 39300342, 2024). "In addition, KDM2B has been reported to have multiple roles in human diseases, the real efficacy of KDM2B on sepsis needs to be investigated in animal models or in vivo experiments." (PMID 37773725, 2023). "Thus, more efforts should be made to investigate the effects of KDM2B on sepsis patients, including the long‐term effect, possible side‐effect, and protective rate." (PMID 37773725, 2023). "However, the role of KDM2B in sepsis‐induced RTEC injury is unclear." (PMID 37773725, 2023). "However, the role of KDM2B in sepsis‐induced AKI is unclear." (PMID 37773725, 2023). "Our research adds to this understanding, showing that circMAPK1 was upregulated in sepsis patients and exacerbates lung injury, primarily regulated NLRP3-mediated macrophage pyroptosis via UPF1/KDM2B/WNK1/NLRP3 pathway." (PMID 39300342, 2024). "KDM2B and WNK1 were markedly decreased in the blood samples of patients with sepsis-induced lung injury, compared with that of healthy volunteers." (PMID 39300342, 2024). "In summary, we hypothesized that circMAPK1 facilitated KDM2B mRNA decay via recruiting UPF1, and the inhibition of KDM2B-mediated WNK1 demethylation further suppressed WNK1 expression, thus triggering NLRP3-mediated pyroptosis in sepsis-induced ALI." (PMID 39300342, 2024). "In conclusion, our findings illustrated that circMAPK1 promoted KDM2B mRNA decay via recruiting UPF1, thereby inhibiting KDM2B-mediated WNK1 demethylation to suppress WNK1 expression, and ultimately triggering NLRP3-mediated pyroptosis to exacerbate sepsis-induced lung injury." (PMID 39300342, 2024).
angiosarcoma (1 paper, 2021). A malignant tumor arising from the endothelial cells of the blood vessels. "KDM2B silencing in angiosarcoma cells enhances cell death via inactivation of DNA repair." (PMID 35008848, 2021).
autism spectrum disorder (1 paper, 2023). A spectrum of developmental disorders that includes autism, and Asperger syndrome.
Azoospermia (1 paper, 2024). Absence of any measurable level of sperm,whereby spermatozoa cannot be observed even after centrifugation of the semen pellet. "It has also been found that KDM2B inhibits the expression of somatic genes and thus inhibits somatic differentiation during the specification of human primordial germ-cell-like cells, which may be one of the reasons for the azoospermia phenotype in nIHH patients." (PMID 37679557, 2024).
Beckwith-Wiedemann syndrome (1 paper, 2019). Beckwith-Wiedemann syndrome (BWS) is a genetic disorder characterized by overgrowth, tumor predisposition and congenital malformations. "Interestingly, two patients presenting with the microdeletion, involving also KDM2B, were initially diagnosed with Beckwith Wiedemann syndrome (BWS) because of overgrowth and macroglossia, which are typical for BWS (MIM 130650)." (PMID 31685013, 2019).
brain cancer (1 paper, 2024). A primary or metastatic malignant neoplasm affecting the brain. "Regarding crosstalk, G9a, GLP, and KDM2B interacted with and influenced other HMTs and HDMs in three types of brain cancer to enhance demethylation." (PMID 39765675, 2024).
cardiac ischemia (1 paper, 2023). "Moreover, cardiac ischemia/reperfusion injury in mice demonstrated that KDM2B knockdown reduced LDH release and improved heart function, suggesting a protective effect against ischemic injury." (PMID 37773725, 2023).
cervical squamous cell carcinoma (1 paper, 2023). A squamous cell carcinoma arising from the cervical epithelium. "ALX3 is a member of the homeobox family with oncogenic potential in cervical squamous cell carcinoma through the transactivation of CDC25A by recruiting lysine demethylase 2B." (PMID 37760434, 2023).
Coffin–Siris syndrome-9 (1 paper, 2023). "A tree-and-leaf plot showed that the JARID2 genome-wide DNA methylation change is most closely related to the DNA methylation changes of Coffin–Siris syndrome-9 (CSS9; SOX11), myopathy, lactic acidosis, and sideroblastic anemia 2 (MLASA2; YARS2) and Lysine-demethylase 2B (KDM2B)." (PMID 37762546, 2023).
dementia (1 paper, 2017). Loss of intellectual abilities interfering with an individual's social and occupational functions. "Targeted re-sequencing of the six candidate genes (LTF, MME, UBE4A SORL1, FAM221A and KDM2B) was performed in 35 EOAD cases with a family history of dementia." (PMID 28595629, 2017).
ependymal tumor (1 paper, 2021). A group of neoplasms which arise from the ependymal lining of the cerebral ventricles and from the remnants of the central canal of the spinal cord. "Among the tumors initially diagnosed as ependymal tumors, a diagnosis was established in 4 cases (50%), including 2 tumors finally diagnosed as infantile hemispheric glioma and HGNET BCOR with a novel fusion (KDM2B:NUTM2)." (PMID 33803647, 2021).
Ewing sarcoma (1 paper, 2024). A small round cell tumor that lacks morphologic, immunohistochemical, and electron microscopic evidence of neuroectodermal differentiation. "Similarly, KDM2B was upregulated in Ewing sarcoma and correlated with worse prognosis, and KDM3A was also found to promote the migration in vitro and metastasis in vivo of Ewing sarcoma." (PMID 39766049, 2024).
Hodgkins lymphoma (1 paper, 2017). A heterogeneous group of malignant lymphoid neoplasms of B-cell origin characterized histologically by the presence of Hodgkin and Reed-Sternberg (HRS) cells in the vast majority of cases. "Anderton and collaborators reported the EBV-mediated deregulation of KDM6B and its role in Hodgkin’s lymphoma, however no previous study has assessed the role of KDM2B in the process of EBV-mediated B cells transformation." (PMID 28724958, 2017).
invasive carcinoma (1 paper, 2017). A carcinoma that is not confined to the epithelium, and has spread to the surrounding stroma. "Finally, among invasive carcinomas, KDM2B expression is higher in lymph node metastases, rather than in the primary tumor." (PMID 28515962, 2017).